CRP (C-reactive protein)
Diseases named in the same sentence as CRP in open-access papers (continued):
Sharing a sentence is not in itself a finding about the gene and the disease.
cardiovascular disease (continued). "In another meta-analysis of advanced biomarkers in cardiovascular disease (CVD) among asymptomatic adults, hs-CRP and NT-proBNP predicted incident events but IL-6 was observed to have stronger associations in certain settings." (PMID 41375916, 2025). "For the diagnostics of cardiovascular disease, SPR biosensors have also been successfully used to detect biomarkers such as C-reactive proteins (CRP) and S100 beta proteins." (PMID 40559306, 2025). "Factors that were associated with 30‐day mortality on univariate analysis included age, sex, cardiovascular disease, COPD, delayed diagnosis, surgical delay, white blood cell, CRP, BUN, and RAR." (PMID 39993970, 2025). "Previous studies have highlighted the importance of the CRP/albumin ratio (CAR) as a sensitive and accessible inflammatory index in cardiovascular disease." (PMID 40506944, 2025). "Some non-CKD–MBD biomarkers, such as asymmetric dimethylarginine (ADMA), resistin, and C-reactive protein (CRP), were demonstrated to be related to a number of cardiovascular diseases." (PMID 40283096, 2025). "While this sensor was designed for cardiovascular disease, it provides a valuable foundation for developing similar optical biosensors for IBD, as CRP is also a key inflammatory biomarker in IBD." (PMID 41244339, 2025). "PIR,ratio of family income to poverty;HB,haemoglobin;CRP, C reactive protein;TC, Total cholesterol;CVD, Cardiovascular disease." (PMID 40378149, 2025). "In patients with cardiovascular disease, dietary PUFA levels were inversely correlated with inflammatory markers, including C-reactive protein (CRP) and interleukin 1β (IL1β)." (PMID 39664126, 2024). "CRP, one of the inflammation markers used in calculating DII, is an independent predictor of cardiovascular disease in end-stage kidney disease patients." (PMID 38386646, 2024). "Furthermore, moderate associations between hs-CRP and various cardiovascular disease risk biomarkers, including a negative correlation with apo A-1 and positive correlations with total cholesterol (TC), TC/HDL-C, and LDL-C/HDL-C, along with a mild positive correlation with HOMA-IR." (PMID 39141186, 2024). "Equal numbers of the OCP users and naturally menstruating elite females were considered to have an intermediate risk of cardiovascular disease (CRP 1–3 mg L−1), a result that may be due to the lack of standardization of the rested blood sample collection protocol." (PMID 37487629, 2023). "The SpyTag/SpyCatcher protein conjugation system was also used for the electrochemical detection of C-reactive protein (CRP), a sensitive serum biomarker of inflammatory/infectious processes, including cardiovascular diseases." (PMID 37630022, 2023). "White blood cell (WBC) count and C-reactive protein (CRP), which are useful and easily available through routine blood tests, are commonly used biomarkers in cardiovascular disease, including ATAAD." (PMID 36937910, 2023). "Even in patients with lower CRP levels, increased RDW and cardiovascular disease mortality were statistically significant." (PMID 37998538, 2023). "In this line, berry consumption markedly diminished CRP and TNF-α levels, decreasing inflammation and preventing the development of cardiovascular disease." (PMID 37513660, 2023). "The main risk factors included in previous PDAP clinical prediction models are age, UA, serum C-reactive protein (CRP)-to-Albumin ratio (CAR), NLR, RDW, DM, and cardiovascular disease." (PMID 37790129, 2023). "In contrast, there are a few researches which found a relationship between B1B1 genotype and lower HDL-C, enhanced C-reactive protein (CRP), and the development of cardiovascular disease." (PMID 37407953, 2023). "Three kinds of antibodies were respectively immobilized on the different GO/SPCEs to capture C-reactive protein (CRP), cardiac troponin I (cTnI), and procalcitonin (PCT) of the cardiovascular disease biomarkers." (PMID 36671960, 2023).
cardiovascular disease (continued). "The data from Mendelian randomization studies coupled with animal studies with injection of human pCRP and transgenic mice over-expressing human CRP may support an association between CRP and cardiovascular disease, but provide no direct evidence for a causative role for pCRP." (PMID 37564640, 2023). "The C-reactive protein (CRP), a prototypical acute-phase reactant, is one of the most widely known biomarkers of cardiovascular disease." (PMID 37571339, 2023). "Studies have shown that inflammation markers such as high-sensitivity C-reactive protein (hs-CRP) and interleukin-6 (IL-6) are elevated in patients with cardiovascular disease." (PMID 37048603, 2023). "A case–control study with a designated experimental group of 110 patients with histories of cardiovascular disease (CVD) showed that s-Klotho levels were significantly lower in the CVD group and inversely correlated with CRP and TNFα/IL10." (PMID 35603960, 2022). "Intake of virgin olive oil, rich in HT, was shown to be more effective than refined olive oil in reducing levels of interleukin-6 (IL-6) and C-reactive protein (CRP), recognized inflammatory markers in cardiovascular disease." (PMID 35408740, 2022). "These included sexes, SOFA score, serum creatinine, CRP at the time of ICU entry, and the presence of cardiovascular disease." (PMID 34170508, 2022). "A rise in inflammatory markers, such as interleukin 6 (IL-6) and C-reactive protein (CRP), are potent predictors of impaired kidney function and the development of cardiovascular disease in CKD patients." (PMID 36359271, 2022). "In addition, less favorable profiles of circulating inflammatory markers including tumor necrosis factor-α, C-reactive protein, and adiponectin in patients with GDM may also contribute to the association between a history of GDM and risk of cardiovascular diseases." (PMID 35865249, 2022). "Elevated C-reactive protein (CRP) and anti-inflammatory adipokines are both important inflammatory biomarkers for cardiovascular diseases." (PMID 34174845, 2021). "Further downstream C-Reactive-Protein (CRP), produced in the liver as a response to IL-6, has been demonstrated to be a sustainable clinical marker of cardiovascular disease." (PMID 34135690, 2021). "In both healthy and metabolically compromised human subjects, quercetin supplementation significantly reduced direct or indirect markers of cardiovascular disorder such as glycemia, total cholesterol, LDL-cholesterol, blood pressure and CRP levels." (PMID 34746258, 2021). "No significant changes were observed between the two groups with regards to markers of cardiovascular disease such as serum-lipid profile (total-cholesterol, LDL cholesterol, HDL cholesterol and triglycerides), hs-CRP, systolic blood pressure or CACS." (PMID 34917038, 2021). "C-reactive protein (CRP) is an independent biomarker of systemic inflammation and a predictor of future cardiovascular disease (CVD)." (PMID 34899053, 2021). "According to the study results, SYM significantly improved the biomarkers of cardiovascular disease including serum procollagen III and C-reactive protein." (PMID 32963577, 2020). "In overweight adults, CP correlates with neutrophil blood count and cardiovascular disease, and with other inflammatory molecules such as IL6 or C reactive protein (CRP)." (PMID 32245056, 2020). "IL-6 and TNF-α stimulate the production of C-reactive protein (CRP) by the liver and, together, trigger the process of subclinical inflammation, which can result in the development of cardiovascular diseases." (PMID 32694929, 2020). "Several previous researches have suggested that numerous inflammatory biomarkers are relevant to cardiovascular diseases (CVD); one of the most typical of these is C-reactive protein (CRP)." (PMID 32546193, 2020).
cardiovascular disease (continued). "Increased levels of C-reactive protein (CRP) and NT-proBNP, along with increased leukocyte numbers, correlated with mortality rate in elderly patients with 2009 H1N1 infections and cardiovascular diseases." (PMID 33193350, 2020). "Increased levels of inflammatory markers, such as interleukin-(IL)-6 and C-reactive protein (CRP), predict the onset of poor health outcomes, particularly cardiovascular diseases and mortality." (PMID 31071114, 2019). "Increased levels of inflammatory markers, such as C-reactive protein (CRP) and serum amyloid A (SAA), are suggested as predictive markers of future cardiovascular disease development." (PMID 31597283, 2019). "This article presents an improved electrochemical impedance measurement system for cardiovascular disease (CVD) diagnosis by detecting CVD biomarkers, S100 beta proteins and C-reactive proteins (CRP)." (PMID 29845100, 2018). "Several inflammatory biomarkers including white blood cell (WBC) count, leukocytesubtypes, platelet, CRP, NLR and PLR have been demonstrated to be importantprognostic predictors in various cardiovascular diseases." (PMID 30043915, 2018). "This study provides several insights into the inter-relationships between inflammation (as measured by CRP), LDL-C, and cardiovascular disease in a population with moderate-to-severe CKD." (PMID 29146277, 2018). "However, some controversy persists regarding whether CRP is a useful predictive biomarker in cardiovascular disease and this may reflect the fact that standard assays measure total CRP, rather than explicitly measuring the pro-inflammatory monomeric structural isoform." (PMID 29946323, 2018). "This article presents a new sensitivity-improved electrochemical measurement architecture for cardiovascular disease (CVD) diagnosis by detecting CVD biomarkers, S100 beta protein and C-reactive protein (CRP)." (PMID 29845100, 2018). "Markers of inflammation, in particular C-reactive protein (CRP) and interleukin 6 (IL-6), have been reported as predictors of cardiovascular diseases." (PMID 28865434, 2017). "In this regard, several markers of the fibrinolytic system and inflammation, such as D-dimer and C-reactive protein (CRP) exert a role in the pathogenesis of renal and cardiovascular disorders." (PMID 27022914, 2016). "The levels of inflammatory markers, such as high sensitivity CRP (hs-CRP), TNF-α and IL-6, are high during inflammation and are related to the pathogenesis of cardiovascular disease." (PMID 26011530, 2015). "C-Reactive Protein (CRP) is a sensitive systemic marker of inflammation and was first identified as a biomarker of cardiovascular diseases." (PMID 24588988, 2014). "The intake of virgin olive oil, rich in polyphenols, was shown to be more effective than refined olive oil in producing a decrease in interleukin-6 (IL-6) and C-reactive protein (CRP) levels, recognized inflammatory markers in cardiovascular disease." (PMID 25988120, 2014). "C-reactive protein (CRP) is a general marker of systemic inflammation and cardiovascular disease (CVD)." (PMID 24763700, 2014). "Moreover, and suggesting an important role for this cytokine in human cardiovascular disease, polymorphisms in IL-38 were associated with CRP concentrations in humans in addition to polymorphisms in CRP, IL-6 receptor, and NLRP3 that were also associated with CRP concentrations." (PMID 23847614, 2013). "In the cardiovascular disease subgroup, the AUCs for the levels of FT3, NT-proBNP and CRP and the APACHE II score in the prediction of ICU mortality were 0.813 ± 0.038, 0.80 ± 0.036, 0.712 ± 0.050 and 0.816 ± 0.038, respectively (all P < 0.001)." (PMID 22257427, 2012). "C-reactive protein (CRP), one of the most frequently used markers, is a major acute-phase reactant synthesized in the liver and is considered a reflection of systemic inflammation across a broad spectrum of cardiovascular diseases." (PMID 41596517, 2026).
cardiovascular disease (continued). "In the Multi‐Ethnic Study of Atherosclerosis (MESA) involving 6814 participants (52.8% women, all without known cardiovascular disease at baseline), women consistently exhibited higher CRP levels than men across all ethnic subgroups." (PMID 41194315, 2026). "Biomarkers such as leukocytes, neutrophils, and C-reactive protein (CRP) can reflect the intensity of the inflammatory response and may serve as prognostic indicators in cardiovascular disease." (PMID 41303851, 2025). "In such a case, a priori study that followed patients with inflammatory arthritis had found that C-reactive protein (CRP), a commonly used marker of systemic inflammation in RA, was an independent predictor of mortality from cardiovascular diseases among this group." (PMID 38903826, 2024). "measured baseline CRP levels in 3,971 older adults without prior cardiovascular disease and conducted a ten-year follow-up." (PMID 39323757, 2024). "CRP serves as an acute-phase reactant and nonspecific marker of inflammation that has proven utility in predicting future development of cardiovascular disease." (PMID 39410926, 2024). "An alleviation of CRP concentration in blood can result from various diseases and is not specific to the process involved in cardiovascular diseases." (PMID 39408337, 2024). "It is worth to highlight that the analyte designated as hsCRP is simply the already-known CRP, i.e., it is not anything new or different, or a novel analyte with any special relationship to Cardiovascular Diseases (CVDs)." (PMID 37873776, 2023). "A meta-analysis of 52 prospective studies that included 246,669 individuals without cardiovascular disease showed that increased CRP levels worsened the 10-year prognosis of cardiovascular risk." (PMID 36768404, 2023). "Furthermore, serine and homocysteine displayed significantly negative correlation with CRP, suggesting that enhanced levels of serine (r=-0.25, p < 0.05) and homocysteine (r=-0.23, p < 0.05) maybe related to low risk of cardiovascular disorders in this population." (PMID 37875989, 2023). "In multivariable linear regression analysis, the Cr/CysC ratio had a negative association with age, female sex, eGFR, cardiovascular disease, current smoking, and the natural logs of ACR and CRP." (PMID 36225865, 2022). "Lastly, this study did not assess novel known markers of cardiovascular disease such as high-sensitivity C-reactive protein, triglyceride and lipoprotein(a) levels along with novel gene scores." (PMID 35935615, 2022). "Although it is evident that acute VTE is associated with an increase in circulating CRP levels, whether long-term, low-grade CRP elevations predicts future VTE events, as it does with cardiovascular disease, remains controversial." (PMID 36177015, 2022). "Furthermore, IL-6 increases the production of C-reactive protein (CRP) in the liver and can indirectly promote the appearance of cardiovascular disorders." (PMID 36362227, 2022). "In another study including individuals without known cardiovascular disease, NGAL predicted cardiovascular mortality independently of traditional risk factors such as renal function and biomarkers such as CRP." (PMID 35456255, 2022). "C-Reactive Protein (CRP) is a nonspecific maker of inflammatory process, the serum levels increase with body insult, tissue damage, aging, and cardiovascular diseases." (PMID 35999949, 2022). "Genetic analyses from Mendelian randomization trials, however, did not support the concept of CRP being actively involved in human cardiovascular disease." (PMID 35407370, 2022). "Inflammation goes hand in hand with the atherosclerotic process, which is important key event of endothelial damage.C-reactive protein (CRP), myoglobin (MYO), creatinine kinase myocardial band (CKMB), cardiac troponins, and myeloperoxidase aresalivary markers of cardiovascular diseases." (PMID 37693919, 2022).
cardiovascular disease (continued). "CRP is a known inflammatory indicator that is commonly detected in blood in higher concentrations among individuals experiencing inflammatory conditions as well as certain conditions such as T2DM and cardiovascular diseases." (PMID 35300754, 2022). "To date, studies pertaining to single nucleotide polymorphisms in the CRP gene and VTE do not suggest a significant association between genetically elevated CRP and VTE risk, which is in contrast to data regarding cardiovascular disease and CRP polymorphisms." (PMID 36177015, 2022). "Since the level of the C-reactive protein (CRP) is a very important parameter in many cases, such as cardiovascular diseases and different kinds of infections, much research is focused on finding new methods to measure this protein with a point-of-care (POC) biosensor device." (PMID 35458884, 2022). "The inflammation biomarker of CRP is found to be elevated in AF patients without coexistent cardiovascular disease." (PMID 33745456, 2021). "C-reactive protein (CRP) is an acute-phase protein that is rapidly produced from the liver and released into the bloodstream in response to various cellular injuries; as such, serum CRP level is widely used as a prognostic marker for cardiovascular diseases." (PMID 34428207, 2021). "They saw increased CRP concentrations at very high serum leptin levels and concluded; CRP did not predict cardiovascular disease independently, unlike leptin, which maintained a statistically significant predictive power." (PMID 34178553, 2021). "These suggested that the effects of IL6 on cardiovascular diseases are independent of the effects of CRP." (PMID 34168680, 2021). "Only a few studies investigated this field assessing the circulating levels of CRP mostly in subjects with LAF and with SHD, without clarifying if this marker is associated with the AF ‘per se’ or rather with the underlying cardiovascular disease." (PMID 32364529, 2020). "Different studies have shown the usage of CRP as a predictor of cardiovascular diseases, however, there are no studies that correlate CRP levels with the severity of RA and extra-articular complications due to anti-HLA antibodies." (PMID 32168865, 2020). "Nonimmunosuppressive treatment lowering the level of hs-CRP has been shown to be beneficial to kidney outcomes and cardiovascular disease in patients with CKD." (PMID 32587865, 2020). "Unlike oxLDL, CRP is not a specific marker of cardiovascular disease, and is not currently considered a target for treatment." (PMID 33271910, 2020). "NPAS3 (Neuronal PAS Domain Protein 3) rs8008403 has not been previously associated with cardiovascular disease related outcomes, but another variant in NPAS3 (rs17460823) was associated with C-reactive protein in patients taking fenofibrate." (PMID 33171725, 2020). "Furthermore, recent evidence has also demonstrated that inflammatory markers such as high sensitivity C-reactive protein (hsCRP)—may not accurately predict cardiovascular disease risk in inflammatory disease states such as systemic lupus erythematosus, psoriasis, and rheumatoid arthritis." (PMID 34327480, 2020). "C-reactive protein (CRP) is a nonspecific inflammatory marker which has been studied extensively in cardiovascular diseases and CRP itself mediate the athero-thrombosis." (PMID 31491986, 2019). "In order to verify the performance of the fabricated LSPR sensor chip, C-reactive protein (CRP), which is a biomarker for cardiovascular disease and inflammation, was selected as a model sample and the detection characteristics of the plasmonic substrate were evaluated." (PMID 31737618, 2019). "C-reactive protein (CRP), the best studied marker of subclinical inflammation, is an acute phase inflammatory reactant that is synthesized in the liver by the stimulation of interleukin-6 and has been proposed as a powerful predictor of cardiovascular disease." (PMID 29558396, 2018).